IL6 (interleukin 6)
Diseases named in the same sentence as IL6 in open-access papers (continued):
Sharing a sentence is not in itself a finding about the gene and the disease.
Sepsis (continued). "The main difference between IL-6 response in sepsis and training is that in sepsis, there is a marked increase in circulating levels of tumor necrosis factor alpha (TNF-α) and IL-1β, prior to the increase in IL-6, which does not happen after acute or chronic physical exercise." (PMID 32765291, 2020). "However, intrigued by the peculiar dynamics of the inflammatory markers during sepsis, especially the lack of IL-6 and CRP response along the high PCT elevation, we prompted investigation of the integrity of IL-6 signaling axis, which we tested in the following steps." (PMID 31781117, 2019). "The in situ decrease (or lack of expression) in Th1 pro-inflammatory cytokines (IL-6, IFN-y, IL-1β, IL-2r, and IL-12) and the increase in IL-10 indicate that there is an inhibition of the innate and acquired immunity during the acute and severe phases of leptospirosis and sepsis." (PMID 31114579, 2019). "Inflammatory cytokine (IL-1, IL-6, etc.)levels increased consistently much more in sepsis than in SIRS, therefore inflammatory mRNAs may act as a “sponge” to sequestrate miRNAs in sepsis, but not in other trauma including SIRS." (PMID 29459855, 2017). "Mediators of sepsis such as lipopolysaccharide (LPS), a gram-negative bacterial cell wall component, triggers apoptosis in cardiac myocytes by promoting the secretion of cytokines such as tumor necrosis factor α (TNF-α), interleukin-6 (IL-6), IL-10, and interferon (IFN)-γ." (PMID 26659076, 2016). "Thus, IL-6 may assist clinicians in assessing NEC disease severity and progression, and in distinguishing between NEC and SIP, but not sepsis." (PMID 27341512, 2016). "The AUCs for IL-2, IL-6, IL-10 and CRP were 0.901 (95% CI, 0.866 to 0.930), 0.86 (95% CI, 0.821 to 0.894), 0.888 (95% CI, 0.851 to 0.918) and 0.848 (95% CI, 0.807 to 0.883) respectively, indicating that IL-2, IL-6 and IL-10 were effective biomarkers to rule out sepsis and intracranial infection." (PMID 24887408, 2014). "Therefore, the effect of IT IL-6 to prevent lung injury was tested; interestingly, lung inflammation was reduced in only direct lung injury and was not affected in AKI-mediated lung injury or sepsis." (PMID 23667439, 2013). "Interestingly, urinary IL-6 was not altered by NAH, indicating that (at least early in sepsis) urine IL-6 may reflect circulating levels of this cytokine as opposed to renal production." (PMID 24400155, 2013). "Likewise, in subjects with and without severe sepsis as well as in subjects with PCT≥0.25, there was an age-related increase in D-dimer (p = 0.02, <0.01, and 0.02, respectively) and no age-related difference in IL-6 (p = 0.86, 0.42, and 0.53, respectively)." (PMID 21085465, 2010). "Attime of diagnosis, serum IL-1β, IL-6, IL-8, and TNF-α levels of culture-provensepsis were significantly higher than those of the control groups (P<.05);but only serum IL-8 levels of culture-proven sepsis was significantly higherthan culture-negative sepsis (P<.05)." (PMID 18274637, 2007). "Interestingly, in a study of 2634 sepsis patients, treatment with the anti-TNF antibody (Ab) afelimomab resulted in a modest but significant reduction in 28-day mortality if serum IL-6 levels were > 1000 pg/mL, while patients with lower IL-6 levels did not benefit from treatment." (PMID 38057824, 2023). "As there was a negative significant correlation between IL-6 and MAP in non-survivors of Group A, maintaining cardiac function via cytokine modulation following CHDF could be an alternative artificial life support in hemodynamic profile of severe sepsis and septic shock." (PMID 37007795, 2023). "However, the most remarkable is the increase of IL-1β, IL-6, IFN-γ, and TNF-α expression in the hippocampus and IL-6, IL-17, and IFN-γ in the PFC 10 days after CLP surgery when the blood culture was negative, and the animals presented a full recovery from sepsis." (PMID 35606817, 2022).
Sepsis (continued). "Because both IL-6 and IL-10 were found in the present study to be increased in CETPTg mice, the consequences of CETP on clinical outcome in relation with cytokine expression should be considered with caution and may not be restricted to sepsis and LPS clearance." (PMID 33500240, 2021). "In addition, CIR-miRNAs in comparison to IL-6, CRP, PCT, and free Hb, generally showed more robust correlations with the APACHE II score, while IL-8 and Prdx-1 had significant positive correlation with the APACHE II score in non-infective SIRS, but not in sepsis." (PMID 29459855, 2017). "Another study showed a significantly increased IL‐6 level and a trend toward higher levels of TNF‐α in Treg‐depleted mice during sepsis, which supported the hypothesis that the hyper‐inflammatory response during the early phase of sepsis was intensified in mice lacking Treg cells." (PMID 28621034, 2017). "Indeed, TNF-α, IL-6, white cell blood count, C-reactive protein or procalcitonin did not correlate with serum ghrelin concentrations neither in all ICU-patients, nor in the subgroups of sepsis and non-sepsis patients in the clinical setting at admission to the Medical ICU (data not shown)." (PMID 20500817, 2010). "Furthermore, no significant decrease in the CRP, PCT, IL-6, leukocyte count, or NLR values was observed in the non-surviving group from Day-0 to Day-5; this ongoing inflammatory response may indicate an ineffective or delayed resolution of sepsis and correlate with disease severity and mortality." (PMID 41155833, 2025).
Insulin resistance (2,752 papers, 2004 to 2026). Increased resistance towards insulin, that is, diminished effectiveness of insulin in reducing blood glucose levels. "A striking example is the failure of IL-6 inhibitors in OA trials: while IL-6 is elevated in OA, its pro-inflammatory effects are tightly linked to insulin resistance and adipokine dysregulation." (PMID 41601721, 2026). "IL-6 mRNA, a key inflammatory cytokine linked to insulin resistance, was also significantly increased in the HFD-fed rats (p < 0.05 vs. control)." (PMID 40867531, 2025). "Aerobic and resistance training lower oxidative stress and improve glucose metabolism, while muscle-derived IL-6 release during contraction enhances insulin sensitivity and reduces the risk of insulin resistance." (PMID 41515940, 2025). "Factors associated with adipose tissue, including tumor necrosis factor alpha (TNF-α), interleukin-6 (IL-6), and IL-1b, are linked to systemic insulin resistance." (PMID 39941760, 2025). "In hepatocytes, a rise in IL-6 bears a close association with the onset of insulin resistance, typically via the downregulation of IRS-1 tyrosine phosphorylation and SOCS-3 expressional upsurge." (PMID 40427505, 2025). "Chronic systemic IL-6 elevation is associated with insulin resistance, while acute IL-6 elevations enhance glucose uptake through AMPK activation." (PMID 41155560, 2025). "Circulating IL-6 stimulates hepatic production of C-reactive protein, a major risk marker for atherosclerosis, and has been implicated in insulin resistance through effects on adipose and hepatic metabolism." (PMID 41007333, 2025). "In general, obesity and insulin resistance are associated with increased proinflammatory cytokines from the adipose, including leptin, IL-6, TNFα, and resistin." (PMID 40985048, 2025). "These ranges are clinically relevant because central obesity and insulin resistance are associated with sustained CRP elevations mediated by IL-6 and other cytokines secreted from visceral adipose tissue." (PMID 41305609, 2025). "Inflammatory markers associated with hyperacute states linked to insulin resistance include IL-6, while hs-CRP is associated with chronic basal inflammation." (PMID 40004236, 2025). "Previous studies have shown that IL-6 levels are associated with insulin resistance and hyperglycemic states, especially in diabetic individuals." (PMID 40005437, 2025). "Research has shown that insulin resistance is closely associated with the excessive production of pro-inflammatory cytokines, including IL-6, IL-1β, and TNF-α, which contribute to disease progression." (PMID 40136627, 2025). "IL‐6 has been implicated in endothelial cell damage, vascular dysfunction, atherosclerosis, and insulin resistance through various cell signaling pathways." (PMID 40630018, 2025). "Elevated levels of IL-6 have been linked to insulin resistance, glucose metabolism, and the development of metabolic disorders." (PMID 40076884, 2025). "Chronic inflammation is a common feature of both conditions, with inflammatory cytokines like tumor necrosis factor-alpha (TNF-α) and interleukin-6 (IL-6) promoting insulin resistance, a hallmark of T2D." (PMID 41007787, 2025). "The results of logistic regression analysis indicate that TNF-α is more strongly associated with abdominal obesity, while IL-6 shows stronger connections with insulin resistance and dyslipidemia." (PMID 40137151, 2025). "Similar results were observed for insulin resistance assessed using HOMA2-IR, where IL-6 was significantly associated with the risk of insulin resistance (OR = 1.068, 95% CI = 1.030–1.107, p < 0.001)." (PMID 40137151, 2025). "Specifically, it seeks to explore the correlation of IL-6 levels with the severity of insulin resistance and to assess the cytokine's potential as a diagnostic biomarker within this patient group." (PMID 40226143, 2025). "Future longitudinal studies would better clarify the temporal dynamics and causal roles of IL-6 in PCOS-associated insulin resistance." (PMID 40226143, 2025).
Insulin resistance (continued). "Dysbiosis can also increase inflammatory cytokines like TNF-α and IL-6, which are linked to insulin resistance and metabolic dysfunction." (PMID 40926269, 2025). "Sarcopenia is often associated with chronic low-grade inflammation, insulin resistance, and oxidative stress, while visceral adiposity contributes to these processes through the secretion of pro-inflammatory adipokines such as IL-6 and TNF-α." (PMID 41245877, 2025). "Elevated IL-6 levels correlate with visceral adiposity, insulin resistance, and increased cardiovascular risk across various conditions." (PMID 41472738, 2025). "This gap underscores the critical need for targeted investigations that can clarify the potential utility of IL-6 as a diagnostic or prognostic biomarker of insulin resistance severity in PCOS populations." (PMID 40226143, 2025). "Persistent liver exposure to IL-6 can contribute to hepatic insulin resistance, while IL-6 trans-signaling and increased hepatic IL-6 expression have been linked to liver stiffness and fibrosis in fatty liver disease." (PMID 41373509, 2025). "IL-6 is also secreted by the placenta, possibly contributing to the inflammatory state implicated in the onset of insulin-resistance during pregnancy." (PMID 40283592, 2025). "Studies have linked IL-6 to the development of insulin resistance and the pathogenesis of type 2 diabetes mellitus." (PMID 41155560, 2025). "Previous studies have shown that there is a significant increase in the expression level of interleukin-6 (IL-6), which contributes to heightened insulin resistance and an elevated risk of cardiovascular complications." (PMID 40519917, 2025). "The results suggest that while TNF-α is primarily associated with abdominal obesity, IL-6 is a strong predictor of lipid disorders and insulin resistance, indicating different mechanisms by which these cytokines influence metabolic disturbances." (PMID 40137151, 2025). "In particular, the increase in cytokines, such as IL-6 in adipose tissue, can elevate the risk of developing insulin resistance, a key precursor to T2D." (PMID 40004236, 2025). "Inflammatory factors produced by macrophages (TNF-α, IL-6, and IL-1β) have been shown to affect lipolysis and cause insulin resistance." (PMID 40764506, 2025). "IL-6 is implicated in the development of insulin resistance, atherosclerosis, and other metabolic disorders." (PMID 41373924, 2025). "Studies have shown that interleukin-6 (IL-6) primarily accelerates muscle loss by inhibiting muscle protein synthesis, enhancing protein degradation, inducing insulin resistance, and suppressing muscle regeneration." (PMID 40255379, 2025). "The role of IL-6 is more controversial, despite the association between circulating levels of IL-6 and insulin resistance." (PMID 40862774, 2025). "IL‐13 neutralizes pro‐inflammatory cytokines (such as TNF‐α and IL‐6), which were associated with the development of insulin resistance in T2DM." (PMID 39355932, 2025). "Elevated IL-6 has been linked not only to disease severity but also to systemic comorbiditiessuch as fatigue, cardiovascular risk and insulin resistance in psoriasis." (PMID 41393395, 2025). "An association of increased IL-6 level with lipid disorders or insulin resistance has also been demonstrated, which translates into hormonal metabolism and some endocrine disorders." (PMID 40647668, 2025). "TNF and IL-6 are central inflammatory cytokines implicated in lipid metabolism disorders and insulin resistance." (PMID 41304686, 2025). "Adipokines, such as adiponectin, and pro-inflammatory markers, including tumoral necrosis factor alfa (TNFα) and interleukin 6 (IL-6), have been implicated in insulin resistance and systemic inflammation in POI." (PMID 40278371, 2025). "Low-grade inflammation in obese patients impacts negatively in insulin signaling pathways and causes insulin resistance, with IL-6 playing an important role in this process." (PMID 41141350, 2025).
Insulin resistance (continued). "IL-6 seems to be implicated in insulin resistance as its plasma concentration is often increased in patients with T2D." (PMID 40943107, 2025). "The existing paradigm of studies suggests that elevated plasma IL-6 levels are associated with obesity, insulin resistance, and MetS." (PMID 40427505, 2025). "As a proinflammatory cytokine with multiple functions, TNF-α is involved in inflammatory activity and DKD-associated insulin resistance, whereas IL-6 and leptin can directly affect renal and endothelial function." (PMID 40936744, 2025). "IL-6 is a key inflammatory mediator in insulin resistance and vascular damage associated with chronic inflammation." (PMID 41268458, 2025). "IL-6, a pleiotropic cytokine associated with chronic inflammation and insulin resistance, has been linked to adverse perinatal outcomes." (PMID 41303355, 2025). "Inflammatory mediators, such as TNF-α and IL-6, interfere with normal insulin function, ultimately leading to the onset of insulin resistance and an increased risk of developing prediabetes." (PMID 40997104, 2025). "MASLD is characterized by chronic low-grade inflammation, which is characterized by increased levels of TNF-α and IL-6, which are in turn associated with insulin resistance and T2DM onset." (PMID 41220583, 2025). "AMP-activated protein kinase activation leads to an increase in insulin-driven glucose elimination, resulting in elevated levels of IL-6, which are commonly associated with increased insulin resistance, a hallmark of T2DM." (PMID 39280507, 2024). "IL-6 causes insulin resistance by impairing the phosphorylation of insulin receptors and receptor substrate-1, inducing the expression of SOCS-3, a potential inhibitor of insulin signaling." (PMID 39051061, 2024). "Conversely, T cell-specific or natural killer cell-specific IL-6R deficiency ameliorated insulin resistance in obese mice, indicating that IL-6 can exert both pro-inflammatory and anti-inflammatory actions." (PMID 38321233, 2024). "IL‐6 is a complicating factor in the causality of sarcopenia because it causes insulin resistance in older adults." (PMID 38270306, 2024). "Leptin, PAI-1, TNFα, and IL-6 levels are elevated in obese individuals and are associated with insulin resistance." (PMID 38317257, 2024). "Although our study also demonstrated that Il6 expression was unchanged in the liver during MASH pathogenesis, the contribution of IL-6 to the systemic insulin resistance associated with MASH should be further investigated." (PMID 39683544, 2024). "Evidence suggests that CHL reduces cortisol, interleukin-6 and insulin resistance, attenuating the surgery-associated inflammatory response." (PMID 39099754, 2024). "On the other hand, although IL-6 causes systemic insulin resistance in MASH, the Il6 mRNA expression is unchanged in the liver of human MAFLD." (PMID 39683544, 2024). "Interleukin-6-mediated inflammation is related to diseased conditions such as insulin resistance, which is associated with diabetes and cancer." (PMID 39684992, 2024). "In fact, IL-1β was observed to have an insulin resistance action, and its increased plasma levels, as well as IL-6, increased the risk of developing type 2 diabetes and plays a role in various metabolic processes." (PMID 38254811, 2024). "In the context of diabetes mellitus IL-6 has been implicated in the development of insulin resistance, a hallmark of type 2 diabetes." (PMID 38667300, 2024). "TNF-α and IL-6 have been associated with impaired intracellular insulin signalling, potentially leading to insulin resistance and further diabetes complications." (PMID 38614881, 2024). "Another research also found that IL6 deficiency aggravated hepatic insulin resistance and inflammation." (PMID 38167327, 2024). "The degree of systemic insulin resistance and plasma IL-6 levels was significantly linked with liver IL-6 expression." (PMID 38535313, 2024).